NOD2 (nucleotide binding oligomerization domain containing 2)
Diseases named in the same sentence as NOD2 in open-access papers (continued):
Sharing a sentence is not in itself a finding about the gene and the disease.
asthma (continued). "The relevant role of NOD1 and NOD2 not only in asthma but also in other diseases with an inflammatory component, such as Crohn ́s disease, has encouraged the development of different compounds with the ability to target their signaling pathways, mainly the adaptor protein RIPK2." (PMID 36189256, 2022). "NOD1 and NOD2, as sensors of microorganisms and cellular stress, have been identified as potential therapeutic targets in a range of autoimmune and autoinflammatory disorders and in diabetes, asthma, atherosclerosis, various forms of CNS diseases and even cancer." (PMID 40666513, 2025). "Moreover, the HDM in vitro stimulation of NOD1 knockdown human bronchial epithelial cells further supported the higher relevance of NOD1 compared with NOD2, in the aggravation of asthma most likely via the differential expression of agonist transporters at the respiratory epithelium." (PMID 36189256, 2022). "However, intranasal infusion of high doses of NOD2 ligands did not break tolerance nor lead to asthma susceptibility, indicating a dose‐dependent effect of NOD2 in allergy development." (PMID 30891811, 2019). "The rs3135499 polymorphism of NOD2 gene and IFN‐β may play a role in the pathogenesis of asthma." (PMID 30950247, 2019). "RIPK2 is the downstream adaptive protein in both the NOD1 and NOD2 signaling pathways, and as such, is a critical mediator in the NOD1 and NOD2-related implication in asthma development." (PMID 36189256, 2022). "NOD2 has a crucial role in the pathogenesis of several pulmonary diseases, including mycobacterial pulmonary diseases, COPD, asthma, and pulmonary inflammatory diseases." (PMID 34440800, 2021). "The variants influence the function of the C-terminal LRR of the NOD2 protein as a sensor for MDP and are likely to play a role in other chronic inflammatory diseases of barrier organs, including atopic eczema and asthma." (PMID 17980027, 2007). "Although the mechanisms are not yet clear in the context of the lung and allergenic asthma, NOD2 can regulate the recruitment of eosinophils, independently of the presence of IgE." (PMID 39507249, 2024). "Subsequently, it was shown that deletion of NOD1 or its downstream adapter RIPK2, but not NOD2, in female mice improved features of asthma." (PMID 39507249, 2024). "In the context of asthma, although many NLR functions and mechanisms are still unknown, it is now clear that at least some of them, namely NOD1, NOD2, and NLRP3, play crucial roles in the development, regulation, and exacerbation of asthma." (PMID 36189256, 2022). "The data suggest that infections in children not sensitized to airway allergens may not participate in the development of asthma through the NOD2 signaling circuitry." (PMID 36233196, 2022). "However, until now, the current studies failed to provide a basis for the genetic correlation of NOD2 variations and asthma in the Chinese populations." (PMID 30950247, 2019).
COVID-19 (15 papers, 2021 to 2025). A disease caused by infection with severe acute respiratory syndrome coronavirus 2. "The similarity analysis demonstrated that genes characterizing NOD2-dependent LY6Clo I-NCMs were enriched in C1 monocytes reported in blood samples from COVID-19–affected humans, including MHC II genes such as HLA-DR." (PMID 39545417, 2024). "NOD2 stimulated with MDP induced 9.2 times lower IL-8 secretion in COVID-19 patients than in healthy subjects (median, pg/mL: MDP: 177 vs. 1634)." (PMID 37189696, 2023). "Among the low-frequency variants extracted, we identified some genes associated with either severity or protection from severe COVID-19 that are linked to the CFTR pathway (e.g., PSMA6) as well as specific genes involved in the immune response (e.g., NOD2)." (PMID 34889978, 2022). "Clinical trials could explore targeted therapies that enhance NAGK function or modulate the NOD2 pathway, aiming to improve outcomes in MS patients with COVID-19." (PMID 39493765, 2024). "A bioinformatics analysis revealed the differential expression of NOD2 in COVID-19 patients." (PMID 36146565, 2022). "NOD2 expression was downregulated in patients with mild COVID-19 compared to healthy individuals." (PMID 36146565, 2022). "However, the secretion of IL-8 induced by NOD2 agonists was lower in COVID-19 patients, indicating that NOD2 may contribute to immunosuppression after hyperinflammation in COVID-19 disease." (PMID 39329913, 2024). "In addition, COVID-19 patients had a lower response to the agonist of NOD2; this innate receptor has been previously reported to recognize viruses through their ssRNA, and NLRs and other members of the inflammasomes are activated during severe COVID-19 and in SARS-CoV-2-infected human monocytes." (PMID 37189696, 2023). "In conclusion, low secretion of IL-8 was observed upon stimulation with TLR2, TLR4, TLR7/8, TLR9, and NOD2 agonists by the blood cells of COVID-19 patients at hospital admission and was restored after two weeks of hospitalization, which may be a contributing factor to immunosuppression." (PMID 37189696, 2023). "Severe COVID-19, however, is characterized by additional activation of TLR1, TLR2, TLR4, TLR5, TLR6, NOD1 and NOD2, which are primarily responsive to bacterial antigens." (PMID 36769320, 2023). "One final complication is that many severe COVID-19 patients are treated with multiple antibiotics, which may further modify the expression of bacterially activated TLR and NOD1/NOD2." (PMID 33672738, 2021). "In particular, severe COVID-19 patients (as well as influenza-associated ALI/ARDS) are characterized by the activation and increased expression of TLR3 and TLR7—two virus-activated receptors—while NOD2 does not appear to play a major role." (PMID 33672738, 2021). "Consistent data indicate that TLR1, TLR5, TLR6, TLR8, NOD1, NOD2 and RIG1 are not activated in severe COVID-19." (PMID 33672738, 2021). "A further reason for thinking that there are likely to be as-yet-unidentified negative feedback systems antagonizing NOD2 and that the antagonistic effects of NOD2 on TLR4 are important in severe COVID-19 is that the interferon (IFN) function is very severely impaired." (PMID 33672738, 2021).
diabetes (15 papers, 2015 to 2025). "Therefore, further investigation is warranted to elucidate the precise role and underlying mechanisms of NOD2 in diabetes." (PMID 39329913, 2024). "On the other hand, NOD2 signaling was shown to be important for the functionality of the metabolism and to be protective against metabolic diseases like diabetes." (PMID 40635891, 2025). "In another study on progressive kidney disease, namely diabetes, it was shown that NOD2 is upregulated and promoted the transcription of extracellular matrix genes and renal injury by inducing inflammation and podocyte insulin resistance." (PMID 29609537, 2018). "NOD2 is upregulated in diabetic cardiomyopathy and silencing this gene could protect against diabetes-induced cardiomyopathy." (PMID 36967805, 2023). "Silencing of NOD2 protects against diabetic cardiomyopathy in a murine diabetes model." (PMID 37724419, 2023). "Moreover, disruption of the gut barrier allowed for the translocation of bacteria to the pLN, which activated the innate receptor NOD2 in immune cells that contributed to diabetes in the STZ-induced diabetes model." (PMID 36059452, 2022). "Although ER stress has been implicated in AS and diabetes, it remains to be elucidated whether the increased inflammatory response after NOD1 and NOD2 stimulation is mediated by UPR activation." (PMID 31109951, 2019). "In line with this, depletion of NOD2 was found to protect against diabetes-induced kidney injury." (PMID 29686650, 2018). "Although genetic variants in NOD1 and NOD2 have not been identified in genome wide association studies (GWAS) of diabetes or other metabolic syndromes, this may not be surprising due to the strong influence that environmental factors have in disease development." (PMID 33503814, 2021). "Nucleotide-binding oligomerization domain containing 2 (NOD2), a member of the NOD-like receptor family, plays an important role in innate immune response and has been shown to be upregulated in the kidney in an experimental model and patients with diabetes." (PMID 29686650, 2018).
periodontitis (14 papers, 2016 to 2025). An acute or chronic inflammatory process that affects the tissues that surround and support the teeth. "TLR2 activation is critical for human gingival epithelial cells and human macrophages to recognise and respond to T. denticola and both TLR9 and NOD2 have been reported to contribute to P. gingivalis-induced bone loss in an experimental model of periodontitis." (PMID 27035339, 2016). "In addition, NOD2 has been linked to the P. gingivalis-induced bone resorption, since NOD2 knockout mice were protected from bone loss in a periodontitis model." (PMID 27531006, 2016). "HGF also diminished the protein level of occludin and upregulated NOD2 expression in mice with periodontitis." (PMID 40427685, 2025). "Nod2 is critical for recognizing bacterial components, amplifying inflammatory responses, and driving NF-κB activation, a central pathway in periodontitis." (PMID 40076622, 2025). "Our results demonstrated that HGF further upregulated the intestinal expression of NOD2 to alter the gut immune barrier when periodontitis occurred." (PMID 40427685, 2025). "NOD1 and NOD2 are two types of NLRs and are involved in the recognition of periodontal pathogens and the process of periodontitis." (PMID 36569059, 2022). "Souza and colleagues induced periodontitis in rats and showed that NOD2 reduced bone resorption and osteoclastogenesis, but the reduction in bone resorption did not affect inflammation as observed by histology." (PMID 35764993, 2022). "Furthermore, the role of PGN during bone resorption in periodontitis was emphasized in P. gingivalis-induced periodontitis in NOD2 knockout mice, which resulted in suppression of RANKL expression and impaired alveolar bone resorption." (PMID 36902030, 2023). "Parvimonas micra can disrupt the normal functioning of the NOD2 signaling pathway in periodontitis, which could potentially lead to a protumorigenic and inflammatory environment." (PMID 35729515, 2022). "It is controversial whether NOD1/NOD2 plays a pro-inflammatory or anti-inflammatory role in periodontitis." (PMID 36569059, 2022). "NOD2 is crucial for bacterial pathogen recognition and its subsequent macrophage response in periodontal tissue, and in agreement with our findings, its knockout was shown to reduce bone resorption in a mouse model of Aggregatibacter actinomycetemcomitans (Aa)-induced periodontitis." (PMID 35844512, 2022). "Additionally, NOD1 and NOD2 in the NLRC family may also participate in inflammation in periodontitis." (PMID 34177950, 2021). "However, Nod2 knockout was shown to decrease osteoclastogenesis and alveolar bone destruction in mouse periodontitis induced by heat-killed A. actinomycetemcomitans, which may be associated with the affected NLRP3 inflammasome activity." (PMID 34177950, 2021).
gastric cancer (13 papers, 2014 to 2025). A primary or metastatic malignant neoplasm involving the stomach. "H.pylori infection leads to the activation of the NOD1 and NOD2 genes; several variants of which have been observed to be associated with gastric cancer in different populations." (PMID 38867324, 2024). "The aim of this study was to assess if polymorphisms of TLR2, TLR4, TLR5, NOD1 and NOD2 genes are associated with gastric cancer, in particular in individuals infected with H. pylori." (PMID 33879265, 2021). "NOD2 facilitates innate immune response in prostate epithelial cells and likely plays a role in PC; NOD2 was also implicated in immunosuppression of gastric cancer." (PMID 33498739, 2021). "Some studies assessing the role of polymorphisms in TLR2, TLR4, TLR5, NOD1 and NOD2 in gastric cancer have been published." (PMID 33879265, 2021). "The aim of our study was to assess the association of common polymorphisms in TLR2, TLR4, TLR5, NOD1 and NOD2 with gastric cancer in H. pylori infected subjects." (PMID 33879265, 2021). "Single nucleotide polymorphisms (SNPs) of NOD1 and NOD2 have been found to be associated with risk of gastric cancers (GC) and precancerous lesions in Caucasian population." (PMID 29254180, 2017). "NOD2 showed a strong genetic association with Crohns's disease, and NOD2 polymorphisms have been associated with gastric cancer and gastric lymphoma induced by H. pylori infection." (PMID 26378020, 2015). "Moreover, genotype TT or CT of rs2066842 NOD2 gene polymorphism was much more common in gastric cancers than in other groups of patients." (PMID 38867324, 2024). "Additionally, gastric cancer patients have mainly genotype TT or CT of the rs2066842 variant of the NOD2 gene." (PMID 38867324, 2024). "NOD2 was implicated in the immunosuppression of gastric cancer." (PMID 35681785, 2022). "The main limitation of most studies on the association of NOD2 gene mutations with gastric cancer was the lack of data concerning H.pylori infection status." (PMID 38867324, 2024). "A lot of researches revealed that the NOD2 gene may be relevant to caners, especially in gastric cancers, but it is the first time that the relationship between NOD2 gene and the prognosis of kidney cancers was revealed by a reanalysis of sequencing data." (PMID 29254180, 2017). "In in vitro experiments, modification of MCEMP1 can affect the invasiveness and metastasis of gastric cancer cells by regulating EMT, in which TLR4/NOD2/NF-κB was involved." (PMID 35378772, 2022).
Listeria monocytogenes infection (13 papers, 2009 to 2025). "Znrf4 knockdown monocytes have sustained nuclear factor kappa-light-chain-enhancer of activated B cells (NF-κB) activation, and Znrf4 knockdown mice have reduced NOD2-induced tolerance and more effective control of Listeria monocytogenes infection." (PMID 28656966, 2017). "In contrast, our results revealed activation of intestinal epithelial cells by Listeria infection in a Nod2-, Ipaf-, and Nalp3-dependent fashion which was followed by ROI production and subsequent MAP kinase signaling." (PMID 21124989, 2010). "For example, defective Nod2 signalling impaired Salmonella typhimurium clearance by intestinal epithelial cells in vitro and decreased host responses to Listeria monocytogenes infection in vivo." (PMID 19841748, 2009). "E. coli has been shown to activate TLR4 and NOD1, whereas resistance to Listeria infection was related to the presence of functional NOD2, indicating that this receptor is engaged by HKLM." (PMID 19193240, 2009). "NOD2 in cooperative with DUOX2 protected against Listeria monocytogenes infection." (PMID 34299310, 2021). "The authors note that a study conducted on a mouse model lacking the CARD15/NOD2 protein found greater susceptibility to Listeria monocytogenes infection." (PMID 30648106, 2018). "Nod1 or Nod2 deficiency alone does not result in a significant alteration in cytokine response to Listeria infection, while cytokine production is downregulated in Rip2KO and Nod1-Nod2DKO macrophages." (PMID 28253332, 2017). "Furthermore, in murine BMDMs, Nod1 and Nod2 seem to have redundant functions with regards to Listeria infection." (PMID 28253332, 2017). "NOD2-dependent RIPK2 activation is essential for an effective antibacterial response, since RIPK2-deficient macrophages have an impaired pathogen control and RIPK2-deficient mice are highly susceptible to listeriosis." (PMID 26834734, 2015). "Previous reports have demonstrated that Nod2 mediates mucosal, but not systemic defence against Listeria infection as demonstrated by significant susceptibility of Nod2 KO mice to infection by bacteria delivered by the oral, but not intraperitoneal or intravenous routes." (PMID 22272321, 2012). "For Listeria monocytogenes infection, NOD2 was shown to be important for restricting bacterial multiplication because Nod2−/− mice orally infected with L. monocytogenes showed decreased production of β-defensins and an increased bacterial burden." (PMID 23162548, 2012). "Activation of RIPK2 by the Lm-sensing intracellular pattern-recognition receptor NOD2 is essential for the downstream stimulation of the NF-κB and MAPK pathways, NOD2-induced immune responses in macrophages and the control of listeriosis in vivo." (PMID 26834734, 2015).
pneumonia (13 papers, 2013 to 2025). An acute, acute and chronic, or chronic inflammation focally or diffusely affecting the lung parenchyma, caused by an infection in one or both of the lungs (by bacteria, viruses, fungi, or mycoplasma.). "We have previously demonstrated that the amino acid polymorphisms TLR5-1205C/T, NLRP3-2906A/G, and NOD2-2197A/C in PRRs in pigs, which have been shown to alter pathogen recognition and cytokine production at the cellular level, are also associated with pneumonia severity in commercial pig farms." (PMID 39202462, 2024). "To test whether the reduced phagocytic capacity of leukocytes in vitro results in impaired host defense during pneumonia in vivo, we infected Nod2-/- and Wt mice with S. pneumoniae D39 via the airways." (PMID 26673231, 2015). "During pneumonia caused by S. pneumoniae D39 Nod2-/- mice were indistinguishable from Wt mice with regard to bacterial loads in lungs and distant organs, lung pathology and neutrophil recruitment." (PMID 26673231, 2015). "Considering that NOD2 has been found to contribute to S. pneumoniae induced inflammatory responses in macrophages, we studied the extent of lung inflammation in Nod2-/- and Wt mice during pneumonia." (PMID 26673231, 2015). "The NOD2-2197C genotype mildly augments the molecular function of NOD2 in comparison with NOD2-2197A, which may contribute to a moderate immune response to exert anti-microbial activity of the hosts and avoid excessive inflammation, which exacerbates pneumonia." (PMID 34573406, 2021). "However, using a sub-lethal mouse pneumonia model, Nod2-deficient mice elicit early enhanced production of inflammatory cytokines and chemokines during A. baumannii infection, suggesting that Nod2 is required for the early but not the late innate immune clearance of A. baumannii pneumonia." (PMID 32391015, 2020). "Lung inflammation was not altered in Nod2-/- mice during S. pneumoniae pneumonia, except for elevated levels of IL-6 and MIP-2 in whole lung homogenates." (PMID 26673231, 2015). "Likewise, the non-inflammasome forming NLR, NLRC2/NOD2, plays a role in neutrophil recruitment and bacterial killing during E. coli-mediated pneumonia in mice." (PMID 23577168, 2013).